SAA1 (serum amyloid A1)
Diseases named in the same sentence as SAA1 in open-access papers (continued):
Sharing a sentence is not in itself a finding about the gene and the disease.
tumor (continued). "The role of SAA1, accompanied by LCN2 expression, was predicted to lead to tumor suppression in this study." (PMID 35705840, 2022). "To make our study more precise, we also analyzed the expression of SAA1 in the UALCAN and GEPIA online tumor database websites." (PMID 34084746, 2021). "Resistant tumor cells highly expressed LINC00160 to recruit transcriptional factor TFAP2A, which bound to SAA1 promoter regions and activated its expression." (PMID 32921632, 2020). "In those studies, recombinant SAA1 media concentrations of 10 μg/mL were used to treat C2C12 myotubes, this corresponds to reported SAA1 concentrations in plasma of tumor‐bearing mice and non‐small‐cell lung cancer patients." (PMID 33063952, 2020). "These can be expressed by inducing an EMT (BHLHE41, NDUFA4L2), a decrease in the adhesive properties of tumor cells (C1QA), and activation of inflammatory reactions (SAA1)." (PMID 31936274, 2020). "Together, SAA1 from GBM was determined to increase the invasion and migration of not only tumor cells but also normal astrocytes, thus promoting the infiltration of GBM cells into the normal brain region." (PMID 29603594, 2018). "SAA1 and SAA3 are effectors of the metastasis-promoting functions of the small calcium binding protein S100A4, providing a link between inflammation and tumour progression." (PMID 26512722, 2015). "At the protein level, SAA1 expression was also increased in tumor tissues relative to adjacent non-tumor tissues, with immunohistochemistry showing predominant localization in the intercellular space." (PMID 41029721, 2025). "Several studies have shown that SAA1, as a nonspecific tumor marker and independent prognostic factor, plays an important role in the diagnosis and prognosis of ovarian cancer, lung cancer, colorectal cancer, pancreatic cancer, renal cancer and other tumors." (PMID 38446289, 2024). "Then, we clustered tumor cells using the FindClusters function with a resolution parameter of 0.3 in GSE159115, and we identified a tumor subtype, PLOD2 + SAA1 + ccRCC cells, which showed higher MECRGS scores, CNV scores, and stemness scores, suggesting a malignant status." (PMID 38951896, 2024). "Moreover, our investigation of single-cell RNA datasets revealed that tumor cells expressing high levels of PLOD2 and SAA1 exhibited enhanced malignancy, as indicated by elevated MECRGS scores, stemness, and copy number variations (CNVs)." (PMID 38951896, 2024). "In addition, acute phase proteins (ORM1, CRP, SAA1) and complement cascade components (SERPINA1, C5, FGA) showed an obviously significant correlation with tumor size, reflecting a positive connection between inflammatory response and tumor size." (PMID 37460463, 2023). "Serum SAA1 has been identified as a biomarker of distant metastases, but it’s not an early tumor marker in RCC patients." (PMID 37081987, 2023). "For example, an 80-year-old ccRCC patient with a 10 cm T3 tumor, positive lymph node, no distant metastasis, G2 tumor, high PD-L1, and high SAA1 had a total score of 310.5 (=72.5 + 55 + 75 + 28 + 10 + 57.5 + 12.5)." (PMID 37108666, 2023). "It was shown in the data that SAA3, SAA1/2, and CitFbg were present not far from the metastatic tumor cells." (PMID 37620307, 2023). "In particular, most of the mRMR genes (n = 7) were obtained from the differential gene expression analysis (DEA) comparing normal tissues versus primary tumor samples, with a larger number of upregulated genes, including the mRMR genes HHLA2, LINC01732, SAA1, AL353637.1, and ZIC2." (PMID 35565241, 2022). "Most importantly, serum SAA1 was identified as a biomarker of distant metastases but not as an early tumor marker in RCC patients." (PMID 34084746, 2021).
tumor (continued). "Tumor markers (CEA, CYFRA 21-1, and NSE) were measured in the patients’ sera and plasmas, along with IL-6, TNF-α, SAA1, CRP, MMP-2, MMP-9, glucose, lactate, and LDH, utilizing enzyme-linked immunosorbent assays, enzyme immunoassays, and automated clinical chemistry and turbidimetry systems." (PMID 34439874, 2021). "Although the role and mechanisms of SAA1 in GBM are still unclear, previous research speculates SAA1 may influence tumor progression by participating in a molecular network that connects inflammation, cell proliferation and angiogenesis." (PMID 33854635, 2021). "We found enhanced SAA1 in infiltration areas surrounding tumors by performing a region‐specific microarray analysis and immunostaining of SAA1 in the GBM animal tumor." (PMID 29603594, 2018). "Together, these findings suggest that SAA1 is highly expressed around tumor infiltration regions rather than the CSC." (PMID 29603594, 2018). "In AA tumor samples, there was no staining detected for SAA1, whereas intense staining was detected for P1/P2-HNF4α." (PMID 28938650, 2017). "Despite much higher SAA-1 levels in the tumor-bearing mice than in controls, indicative of tumor-induced inflammation, hepcidin mRNA concentrations were not increased proportionally in TC-1-bearing mice and were even decreased in LLC-bearing mice." (PMID 24681760, 2014). "Surprisingly, SAA1 does not directly promote tumour cell proliferation or migration." (PMID 42145073, 2026). "Consistent with these mechanistic insights, clinical analyses revealed that elevated levels of SAA1, IL1B, and CD33+ MDSCs were significantly correlated with poorer overall survival in EOC patients, underscoring the SAA1/IL-1β/MDSC axis as a key driver of tumor progression and adverse prognosis." (PMID 41029721, 2025). "Additionally, we discovered a distinct ccRCC tumor cell subtype characterized by the high expressions of PLOD2 (procollagen-lysine,2-oxoglutarate 5-dioxygenase 2) and SAA1 (Serum Amyloid A1), which we further validated in the Renji tissue microarray (TMA) cohort." (PMID 38951896, 2024). "In contrast, tumor cells may be more prone to cellular stress in the absence of SAA1/2 and may upregulate autophagy as a cell protective response for survival." (PMID 36248994, 2022). "However, experimental validation regarding the correlation between SAA1 expression in tumor tissues and immune cell infiltration is lacking, which is one of the major limitations of this study." (PMID 35756918, 2022). "On the other hand, SAA1 phenotype, such as SAA1.5, has no tumor-suppressive effect." (PMID 35705840, 2022). "Our analysis found that the mRNA expression of SAA1 was positively correlated with these clinicopathological parameters and that the mRNA expression of SAA1 increased significantly in higher tumor stages but did not increase or show a downward trend in early tumor stages." (PMID 34084746, 2021). "Moreover, another study reported that serum SAA1 has been identified as a biomarker of distant metastases but not as an early tumor marker in RCC patients." (PMID 34084746, 2021). "However, studies examining whether tumor cells contribute to tumor immune escape by regulating MDSCs through SAA1 are currently lacking." (PMID 41029721, 2025). "Notably, we reported that expression of MFI2-AS1 was associated with expression of acute-phase proteins such as IL6 and SAA1, which might indicate that MFI2-AS1 is involved in the positive regulation of genes responsible for tumor-promoting inflammation, a poor prognosis factor in ccRCC35." (PMID 28819235, 2017). "ROC curve analysis found that SAA1 could only distinguish patients with advanced and metastatic ccRCC from the normal population, while Kaplan Meier curve analysis indicated that high SAA1 expression always predicted a worse prognosis regardless of tumor stage." (PMID 34084746, 2021).
tumor (continued). "In addition, although NP mice exhibited significantly shorter tumor-free survival compared to N mice, and SAA1, SAA2, and THBS4 enhanced HER2/neu+ cancer cell proliferation in vitro, Ki67 staining of tumor sections did not reveal differences in proliferation between N and NP tumors." (PMID 41387465, 2025). "Lastly, the proliferation marker MCM2 did not significantly change following double knock out of SAA1/2 in vivo, however, the inhibition of autophagy with CQ significantly increased the expression of MCM2 in the SAADKO group when compared to the untreated WT and SAADKO tumor groups." (PMID 36248994, 2022).
infection (87 papers, 2010 to 2026). The state of being infected such as from the introduction of a foreign agent such as serum, vaccine, antigenic substance or organism. "In this regard, we found that DHA supplementation produced an important reduction in Saa1, that encodes for an acute phase protein that is mainly produced by the liver in response to tissue damage, inflammation, and infection." (PMID 41373837, 2025). "SAA1 encodes an acute phase protein that is highly expressed during tissue injury, inflammation, or infection." (PMID 35706505, 2022). "Upon infection, SAA1 levels increase dramatically and its association with HDL has been demonstrated to reduce the lipoproteins’ anti-inflammatory properties and its cholesterol efflux capacity." (PMID 35577388, 2022). "Among the common proteins that were increased in abundance, all (Saa1, Lrg1, Hpx, Hp, Itih4, Serpina3n, Fga/b/g, Cp, and C3) were associated with the acute-phase response to infection." (PMID 32843537, 2020). "SAA1 can bind retinol and can provide it during an infection – mice deficient in both SAA1 and SAA2 have increased bacterial numbers in spleen and liver following acute infection." (PMID 30165816, 2018). "To evaluate the capacity of SAA1/2 measurement to rule-in patients at risk of infection, we set specificity (SP) at between 90 and 100%." (PMID 28701906, 2017). "In contrast, at peak infection (i.e. 7 days p.i.), expression of mRNA encoding for acute phase protein serum amyloid A1 (Saa1) was lower (p ≤ 0.044) in mice administered both CTC and TYL." (PMID 27929072, 2016). "Among the upregulated genes there are genes that belong to infection-associated inflammatory Acute Phase proteins (APPs), such as Serum amyloid A1 (SSA1, FC = 1599) and A2 (SSA2, FC = 49), colony stimulating factor CSF2 (FC = 1316) and CSF3 (FC = 234), as well as Ceruloplasmin (CP; FC = 46.49)." (PMID 35531332, 2022). "In all kinds of infections with either viruses, bacteria, fungi and parasites, the cytokines IL-1, IL-6, and TNF-α induce considerable amounts of SAA1 in the liver and minute amounts of specific chemokines at entry and propagation sites of infections." (PMID 40076881, 2025). "To benchmark these findings, we evaluated two well-known clinical biomarkers of inflammation, C-reactive protein (CRP) and serum amyloid A (SAA1), which are commonly used to monitor infection progression." (PMID 39835799, 2025). "Despite the recognized roles of CRP and SAA1 in modulating immune responses during infection, the specific function of SAA1 in the early stage of S. pneumoniae infection remains poorly defined." (PMID 40572197, 2025). "SAA1 is a member of the serum amyloid A family of apolipoproteins expressed during the initial response to infection and trauma." (PMID 41028049, 2025). "Serum amyloid A1 (SAA1) is an inducible acute phase protein in response to injury, infection and inflammation and has been identified as a novel proinflammatory oncoprotein whose levels progressively increase with AML progression." (PMID 40299483, 2025). "Our studies on chemotactic factors present in serum or plasma yielded several surprising novel insights about the regulation of inflammation in infections and the biology of the acute phase reactant SAA1." (PMID 40076881, 2025). "Overexpression of Saa1, Saa2, Saa3, and Saa4 in macrophages enhances NF-κB-mediated pro-inflammatory cytokine production and bacterial clearance during infection." (PMID 40061939, 2025). "Surprisingly, CRP levels remained unchanged after infection, while SAA1 levels significantly decreased." (PMID 40572197, 2025). "SAA1 regulates the chemotaxis of inflammatory cells, attracting neutrophils and monocytes to the infection site, and interacts with TLR2/4 to activate immune cells." (PMID 40572197, 2025).
infection (continued). "SAA1/2 is highly expressed in the liver in response to inflammatory stimuli, such as tissue injury, infection, and trauma, and once secreted into the circulation, it becomes a major apolipoprotein of high-density lipoprotein (HDL)." (PMID 40429677, 2025). "Serum Amyloid A1 (SAA1) is an acute phase protein that is primarily produced by hepatocytes in response to infection, tissue damage and malignancy." (PMID 39001884, 2024). "SAA1 is a major acute-phase protein mainly produced by hepatocytes in response to infection, tissue injury, and malignancy." (PMID 38699144, 2024). "As a major acute-phase apolipoprotein reactant, SAA1 was mainly in the liver and responsible for responding to infection, potential injuries, and malignancy." (PMID 37108666, 2023). "Serum amyloid A1 (SAA1), an acute-phase protein produced in response to inflammation, infection, and trauma, has also been found to be increased in PCOS patients." (PMID 37929034, 2023). "Among genes involved in the inflammatory response, S100A9 and SAA1 were upregulated in response to experimental infection in birds from both less-tolerant and more-tolerant populations." (PMID 37294834, 2023). "Serum Amyloid A 1 (SAA1) is an acute-phase protein mainly produced by hepatocytes in response to infection, tissue injury and malignancy." (PMID 35565241, 2022). "Two of them, SAA-1 and sCD25, have also been found to be excellent markers of infection in children in the present study." (PMID 35329889, 2022). "CRP and SAA1 are positive APPs, and their correlation has been described in different physical conditions, including infection, trauma, inflammatory reactions, and hypermetabolic diseases, including prognosis of COVID-1924–27." (PMID 36400821, 2022). "SAA1-opsonization of Mtb prior to the infection of human macrophages favored bacterial entry into target phagocytes accompanied by a substantial increase in the load of intracellularly multiplying and surviving bacteria." (PMID 34065319, 2021). "The coregulated protein serum amyloid alpha 1 (SAA1) shows highly similar fold changes upon infection and is likewise covered, resulting in a more inclusive reflection of an individual’s inflammation status than the routine assessment of CRP alone." (PMID 33444735, 2021). "An obvious question that arises as a consequence of the proven ability of Mtb to specifically bind SAA1 is the importance of this interaction over the course of infection with this pathogen." (PMID 34065319, 2021). "Previous studies have shown that SAA1 plasma levels have increased dramatically in response to tissue damage, infection, and various emergencies." (PMID 32695227, 2020). "Saa1 is produced in response to severe infection and other forms of environmental insults and is served as a clinical diagnosis biomarker of inflammation." (PMID 33101287, 2020). "In contrast to EPO and G-CSF which are hematopoietic cytokines, SAA1 is an acute phase protein, primarily produced by the liver, and elevated in the plasma following trauma, infection, inflammatory reactions, and cancer." (PMID 30778109, 2019). "In agreement with the transcriptional upregulation of inflammatory cytokines observed in the livers of P. chabaudi-infected mice, there was a > 30-fold induction of Saa1/2 mRNA at days 6 and 12 post-infection." (PMID 31299982, 2019). "Gelatinase B or matrix metalloproteinase-9 (MMP-9) is also induced by SAA1 during infection and inflammation and processes many substrates in the immune system." (PMID 29915572, 2018). "Serum amyloid A1 (SAA1) is an acute‐phase high‐density lipoprotein secreted by the liver in response to infection and tissue injury." (PMID 29603594, 2018). "Since SAA1 is a factor released during the acute phase response to infection and other stress challenges, the actions of SAA1 revealed in this study are probably among the earliest events that initiate both normal and pathogen-induced preterm birth." (PMID 28386088, 2017).
infection (continued). "Third, we found that intraperitoneal infection of Saa1/2−/− mice with S. typhimurium resulted in higher bacterial loads in liver and spleen as compared to wild-type mice, suggesting that SAAs also contribute to systemic immunity." (PMID 25073702, 2014). "The up-regulation of an acute phase protein, SAA1, is significant because it suggests an early stage of infection." (PMID 25276097, 2014). "The pattern of increased SAA1 expression observed in PCV2-infected PAMs suggested that PCV2 induced an acute inflammatory response at the early time point (24 HPI) of infection." (PMID 23711280, 2013). "SAA1 was also found as the most up-regulated gene in spleen seven days after infection by H. parasuis." (PMID 20459780, 2010). "Moreover, the decline in SAA1 post-infection implies that S. pneumoniae actively reduce SAA1 levels, possibly via proteolysis or endocytosis." (PMID 40572197, 2025). "As a major acute-phase apolipoprotein reactant, SAA1 was mainly in the liver and responsible for responding to infection, potential injuries, and malignancy; it has also been discovered as overexpressed in various types of cancers and relates with a poor prognosis." (PMID 37108666, 2023). "Apart from partitioning into the HDL fraction in blood and cholesterol transport and recycling, SAA1/2 are also the most conspicuous components of the acute phase response (APR), in which serum levels of SAA1/2 surge sharply in response to trauma, infection, and other stimuli." (PMID 37197655, 2023). "On the other hand, the opsonization of tubercle bacilli by SAA-1 may facilitate the adaptation of mycobacteria to stress conditions during infection." (PMID 37781389, 2023). "During an infection with Citrobacter rodentium, MyD88 signaling in IECs alone was found to be sufficient to improve epithelial barrier integrity and to increase production of RegIII-γ and the acute phase protein serum amyloid A1 (SAA1)." (PMID 37519301, 2023). "SAA1 overexpression may lead to the induction of pro-inflammatory genes as acute response mediators during infection, and they aggravated T cell-mediated hepatitis in mice." (PMID 36423130, 2022). "Genes Saa1 and Slpi were significantly upregulated during infection." (PMID 35573776, 2022). "Levels of SAA1, IL-6, and IP-10 were found to increase after infection." (PMID 34943175, 2021). "In Huh7 cells, increased expression of acute-phase proteins, such as C-reactive protein and serum amyloid A1, was observed with the progression of infection, whereas FFAR2 and STEAP4 with metalloreductase activity showed significantly higher upregulation than other genes." (PMID 34899651, 2021). "What's more, the findings of stimulation of SAA1 expression and secretion by LPS in trophoblasts suggest that fetal placenta may contribute to the SAA1 pool together with maternal liver in the maternal blood in preterm birth with infection." (PMID 32582166, 2020). "The evidence for the involvement of SAA1 in infection-induced inflammation is overwhelming." (PMID 32582166, 2020). "Accordingly, we found increased RNA abundance of Arg1, Socs1, Sra1, Saa1, Ciita, Marco, Mgl2, Cd209d, Cd209e, Cd209f, Ccl1, Ccl11, Ccl17, Ccl19, Ccl20, Ccl22, and Ccl24 genes in Stat2−/− mice when compared to WT mice during super-infection." (PMID 30337919, 2018). "Next, we found increased mRNA expression and activity levels of Arg1, mRNA expression of Fizz, Chi3l3, Cd209d, Cd209e, Mrc2 (Cd206), Marco, Il13, Saa1 (Serum amyloid A1 protein), Ccl17, Ccl19, Ccl20, Ccl22, and Ccl24 in Stat2−/− mice compared to WT mice during super-infection." (PMID 30337919, 2018). "A further increase in the abundance of SAA1 in the amnion is expected in the presence of infection for the reason that the proinflammatory cytokines such as IL-1β could stimulate SAA1 production in cultured amnion fibroblasts." (PMID 28386088, 2017).